UCMA (upper zone of growth plate and cartilage matrix associated)
Description:
May be involved in the negative control of osteogenic differentiation of osteochondrogenic precursor cells in peripheral zones of fetal cartilage and at the cartilage-bone interface.
Synonyms: GRP; C10orf49; GRP/UCMA
Tractability: Antibody: UniProt places it where antibodies can reach, with medium confidence; UniProt predicts a signal peptide or a membrane-spanning region; its Gene Ontology location is reachable by antibodies, with medium confidence.
Gene: Protein-coding gene on chromosome 10 (13,221,762 to 13,234,428, reverse strand). Ensembl gene ENSG00000165623.
Subcellular location: Secreted, extracellular space, extracellular matrix
Pathways (Reactome):
Gene expression (Transcription): RUNX2 regulates osteoblast differentiation
Gene Ontology:
Molecular function: BMP binding; protein binding
Biological process: negative regulation of SMAD protein signal transduction; embryonic skeletal system development; regulation of osteoblast differentiation
Cellular component: cytoplasm; extracellular matrix
Genetic constraint (gnomAD): Loss-of-function variants: 21 observed, 23.18 expected, observed/expected ratio (o/e) 0.91, 90% interval 0.64 to 1.3. The upper end of that interval is the gene's LOEUF score, 1.3, which puts it in group 5 of 6, group 1 being the genes least tolerant of losing a copy. Missense variants: 193 observed, 187.55 expected, observed/expected ratio (o/e) 1.03, 90% interval 0.91 to 1.16. Synonymous variants: 76 observed, 71.7 expected, observed/expected ratio (o/e) 1.06, 90% interval 0.88 to 1.28.
Homologues: Orthologues: chimpanzee UCMA (99% identical), macaque UCMA (91% identical), guinea pig UCMA (84% identical), rabbit UCMA (83% identical), pig UCMA (82% identical), rat Ucma (82% identical), dog UCMA (80% identical), mouse Ucma (79% identical), tropical clawed frog ucma (62% identical), zebrafish ucmab (49% identical), zebrafish ucmaa (43% identical).
Diseases named in the same sentence as UCMA in open-access papers:
UCMA is named in the same sentence as 7 diseases in open-access papers, as found by Europe PMC text mining. Sharing a sentence is not in itself a finding about the gene and the disease. The quoted sentences say what the papers report.
osteoarthritis (5 papers, 2017 to 2024). A noninflammatory degenerative joint disease occurring chiefly in older persons, characterized by degeneration of the articular cartilage, hypertrophy of bone at the margins and changes in the synovial membrane. "Thus, UCMA/GRP has been shown to protect cartilage from degradation in experimental osteoarthritis and inflammatory arthritis models." (PMID 34502245, 2021).
rheumatoid arthritis (2 papers, 2022 to 2025). A chronic, systemic autoimmune disorder characterized by inflammation in the synovial membranes and articular surfaces. "Gla-rich protein (GRP), also known as upper zone of growth plate and cartilage matrix associated protein (UCMA), is a vitamin K-dependent protein (VKDP) that plays significant roles in several processes related to the development of CIDs such as CVD, OA, rheumatoid arthritis, and CKD." (PMID 41002995, 2025).
UCMA also shares sentences with these, for which no sentence is quoted: cancer (1 paper); cardiovascular disease (1); chronic kidney disease (1); coronary artery disease (1); Dialysis (1).